IDO1 (indoleamine 2,3-dioxygenase 1)
Diseases named in the same sentence as IDO1 in open-access papers (continued):
Sharing a sentence is not in itself a finding about the gene and the disease.
tumor (continued). "Furthermore, IDO1 and catabolite kynurenine are highly expressed in tumor cells to impair T cell fitness by depleting tryptophan and accumulating immunosuppressive metabolites." (PMID 36618408, 2022). "Moreover, various IDO1 inhibitors have been shown to inhibit Trp metabolism, which promotes tumor progression." (PMID 36545214, 2022). "The results reveal that IDO1 gene expression is induced by several tumour-related serine proteases, a phenomenon which may contribute to the suppression of host immunity, the facilitation of bacterial invasion, and oncogenesis." (PMID 35371018, 2022). "Previous studies have found that IDO1 promotes tumor immune escape." (PMID 35571116, 2022). "These IDO1-expressing cells, including MDSCs, DCs, and macrophages, are closely related to the restriction of normal immune response, which is consistent with the high expression of IDO1 in some tumor tissues." (PMID 35681736, 2022). "Generally, the important function of IDO1 in tumor immunology is accepted for two reasons." (PMID 35563059, 2022). "Immune checkpoint blockade (ICB) could induce IL4I1 and IDO1, whereas IL4I1-deficient mice model showed a reduced Treg frequency and tumor burden, indicating the role of IL4I1 in immune escape." (PMID 35962343, 2022). "It manifested that the apoptosis rate of CD8+ cells in LC increased obviously in the IFN-γ+mimics-NC group, but the apoptosis of CD8+ cells was inhibited after coculture, suggesting that upregulating miR-760 suppressed CD8+ cell apoptosis by inhibiting IDO1, thus inhibiting tumor immune escape." (PMID 35872931, 2022). "Therefore, drugs combining IDO1 inhibitors and immune checkpoint inhibitors have been developed for enhancing anti-tumor immunity." (PMID 35280684, 2022). "However, new immune checkpoints such as idolamin-2,3-dioxygenase 1 (IDO1), a key component in tumor microenvironments, are currently being evaluated in clinical trials." (PMID 35053603, 2022). "In order to explore whether miR-760 can regulate IDO1 to participate in tumor immune response, 30 ng/ml of IFN-γ was cocultured with LC cells transfected with miR-760-mimics." (PMID 35872931, 2022). "In some samples, IDO1-positive tumor cells were detected in inflamed areas rich in T lymphocytes." (PMID 36188218, 2022). "It indicates that IDO1 inhibition stimulates NK cells against tumor cells." (PMID 34201791, 2021). "IDO1 was involved in the anti-tumor immune process of both tumors and was related to TMB." (PMID 33509222, 2021). "Besides the direct act on processes promoting oncogenesis, an elevated number of Tregs, and thus IDO1 activity, leads to the development of the immunosuppressive tumor microenvironment." (PMID 34071442, 2021). "Tumor cells use IDO1 expression as a mechanism of immune escape." (PMID 33467713, 2021). "However, there was still controversy about the relationship between high expression of IDO1 in tumor-draining lymph nodes (TDLN) and poor clinical outcomes." (PMID 35003126, 2021). "The main theory about the function of IDO1 is that Trp availability is locally reduced while bioactive metabolites such as Kyn are increased, which mediate immune regulation and immune tolerance involved in the pathological mechanisms of tumor immune escape." (PMID 35003126, 2021). "Overall, these data suggest that under normal (immunocompetent), conditions of tumor growth, there is sufficient immune-dependent IFNγ signaling to drive Ido1 expression, and this can be recapitulated at similar expression levels in vitro by supplementing cultured cells with IFNγ 1 ng/mL." (PMID 33831358, 2021). "Further tumor growth assays are required to more fully characterize this effect—for example, using immunocompetent models in which the combined metabolic and immunomodulatory effects of IDO1 inhibition are taken into account." (PMID 33831358, 2021). "IDO1 has been frequently detected in tumor specimens of patients with HCC (97.3%)." (PMID 34769098, 2021).
tumor (continued). "Further application of 11C-l-1MTrp to monitor therapeutic efficacy in mice treated with one of two IDO1 blockade + chemotherapy regimens showed little ability to distinguish between good and poor responders via tumor PET imaging; a similar phenomenon was reported in a previous study." (PMID 34148865, 2021). "Within a tumor microenvironment, high expression of IDO1 is also indicative of the presence of a population of tumor-infiltrating immune cells such as myeloid-derived suppressor cells (MDSCs) which are known to have suppressive effect on adaptive immune responses." (PMID 34946170, 2021). "As for cancer cell lines, over 16% of tumor cell lines revealed certain expression of IDO1, and 19% of those cells are TDO positive, reminding us that TDO2 might serve as superior target for precise treatment of cancer." (PMID 34657603, 2021). "Moreover, Trp depletion inhibits T cell proliferation, and indoleamine 2,3-dioxygenase 1 (IDO1) facilitates tumor evasion under immune surveillance." (PMID 34394086, 2021). "Furthermore, the heterogeneity of IDO1 expression in tumor tissues also affect the detection results of IDO1 expression." (PMID 33557876, 2021). "In addition, INFγ can upregulate expression of other key immune suppressive molecules such as IDO-1 within the tumor microenvironment." (PMID 33671892, 2021). "The complexity of this phenomenon may be partly because IDO1 is expressed in two compartments, including tumor cells and tumor-infiltrating lymphocytes." (PMID 34322485, 2021). "Overall, these analyses suggest that the measured Ki67 mostly comes from tumor cells in the immune-poor regions, and that co-targeting B7-H3 or IDO-1 in neoadjuvant ICB treatment may potentially improve the treatment outcome for patients with recurrent GBM." (PMID 34188042, 2021). "Down-regulation of COL6A2 induced by decreased IDO1 could suppress host anti-tumor immune response through inhibiting immune-related pathways." (PMID 35127724, 2021). "And both tumor and stromal cells have been proved to exhibit elevated IDO1 activity." (PMID 34657603, 2021). "Moreover, IDO1 seems to promote the inflammatory neovascularization of the tumor site, acting against the anti-angiogenic effect of IFN-γ." (PMID 34453261, 2021). "The overexpression of IDO1 has been observed in many tumor types." (PMID 34657603, 2021). "Finally, we found that blocking the IDO1 enzyme enhanced the cytotoxicity of Vγ9Vδ2 T cells by perforin secretion under tumor burden stress." (PMID 34381711, 2021). "However, in the tumor region, there is a set of DCs highly expressed IDO1 with a high capacity to support immune tolerance." (PMID 35003126, 2021). "Moreover, anti-PD-L1 therapy promotes tryptophan catabolism as a consequence of IDO1 upregulation by IFN-γ secreted by re-invigorated tumour-infiltrating lymphocytes." (PMID 33708223, 2021). "One of the main activators of IDO1 expression in a tumor is INF-γ." (PMID 33466316, 2021). "In addition, IDO1 overexpression is related to increased tumor progression and poor prognosis of tumors, which makes it a promising therapeutic strategy for malignant tumors." (PMID 33718227, 2021). "MDSCs are composed of multiple myeloid cells that are arrested at different stages of lineage development, which would be recruited to the TME by IDO1 overexpressing tumor cells, and then MDSCs inhibit T-cell function and reduce tumor response to immunotherapy in an IDO1-dependent manner." (PMID 35003126, 2021). "Moreover, inhibition of IL-6 production by tumor cells reduces IDO1 expression and tumor-mediated immunosuppressive effects." (PMID 34394118, 2021). "Inhibition of IDO1 may impair the induction of autophagy in tumor cells, the phagocytotic activity of macrophages and even the antigen presenting function." (PMID 33390854, 2021). "Overall, the molecular of IDO1 inhibitor shows promising anti-tumor potential." (PMID 35095898, 2021).
tumor (continued). "Similarly, IDO1 inhibition also inhibits the lung metastasis of breast cancer and improves the survival of tumor-bearing animals." (PMID 34422661, 2021). "In turn, the discoveries concerning the role of IDO1 in tumor angiogenesis suggest that inhibiting its activity may effectively suppress this process, providing a potentially effective solution in the prevention of tumor development and metastasis." (PMID 34201791, 2021). "Regarding the perspective on IDO1-centered dormancy regulation, while current research has devoted to the development of IDO1 inhibitors for active tumour elimination, how these inhibitors may be applied in dormancy models needs further attention." (PMID 34539663, 2021). "To assess whether host- or tumor-derived IDO1 expression leads to upregulation of inhibitory receptors, we analyzed the phenotype of CD8+ TILs isolated from WT and IDOKO mice bearing either IE9mp1-mIDO1 or IE9mp1-EV tumors." (PMID 34025677, 2021). "We acknowledge that these results are described in an overexpressing IDO1 tumor model." (PMID 34025677, 2021). "IDO1 is expressed in tumor infiltrating T cells and its enzymatic activity converts tryptophan to kynurenine – a molecule which reduces cytotoxic T and NK cell activity, while promoting the expansion of immunosuppressive regulatory T cell and myeloid derived suppressor cell populations." (PMID 34277419, 2021). "Imatinib in experimental tumor models potently reversed IDO1-mediated immunosuppression." (PMID 34201791, 2021). "Tumoral IDO1-induced KYN was sufficient to upregulate PD-1 on CD8+ T cells in vivo and in vitro." (PMID 34025677, 2021). "Since IDO1 is an immunosuppressive component of the tumor storm, it can be assumed that its high expression may be associated with a poor prognosis." (PMID 33466316, 2021). "Thus, the unbalanced metabolism of tryptophan can promote tumor development and evade immune detection indicating that the application of IDO1 inhibitor is also a promising means to enhance antitumor immunity in theory." (PMID 34917131, 2021). "In conclusion, IDO1 is a key mediator in the establishment of tumor immune escape." (PMID 35003126, 2021). "However, at some point, it is relevant to link the anti-tumor outcome of 1-D-MT to the induction of IDO1 by IFN-γ." (PMID 34943977, 2021). "This difference between tumour subpopulations might be explained by their distinct expression profiles that TRCs exhibit higher levels of IDO1 and AhR than differentiated tumour cells do." (PMID 34539663, 2021). "This study provides new insights into the role of IDO1 as a novel enzyme source of NO in tumours." (PMID 34685679, 2021). "However, how the high level of IFN-stimulated IDO1 expression in tumours is related to the IDO1 levels in DCs during dormancy remains to be explored." (PMID 34539663, 2021). "IDO1 expression may be induced by the secretion of IFN-γ by CD8+ T cells in the tumor microenvironment." (PMID 34778035, 2021). "A potential explanation for the confined IDO1 expression could be due to the presence of inflammatory cytokine(s) in the tumour microenvironment that activate IDO1 activity." (PMID 34680327, 2021). "This differential tumor-specific therapeutic potential highlights the importance of IDO-1 expression for efficient photodynamic immunotherapy, and provides novel insights into the development of new multifunctional nanoprobes to overcome adaptive immune resistance." (PMID 34158855, 2021). "Additionally, recent preclinical evidence indicates that the IDO1 inhibitors synergize the effects of tumor immuno- and chemotherapies and help to solve the problem of tumor resistance against them." (PMID 34201791, 2021).
tumor (continued). "However, some of the specimens also had infiltration of immunosuppressive regulatory T cells and upregulation of IDO1, PD-L1, and IL-10, suggesting that the infiltration of EGFRvIII cells within the tumor incited a compensatory immunosuppressive response." (PMID 34421912, 2021). "Based on these mechanisms, IDO1 expression in tumor sites and circulating Trp and Kyn (evaluated as the Kyn/Trp ratio) have been hypothesized as possible markers of cancer progression." (PMID 33922388, 2021). "Despite the pro-tumor effects of IDO1, the specific role of TDO2 in cancer remains controversial." (PMID 34657635, 2021). "Therefore, prolonged IDO1 overexpression in the tumor microenvironment negatively correlates with patient outcomes." (PMID 34201791, 2021). "Of note, the staining patterns of IDO1 varied widely according to the tumor type." (PMID 33557876, 2021). "In tumor cells, IL-6 upregulates IDO1 expression and favors tumor immune escape mechanisms." (PMID 34394118, 2021). "However, 24, 6, 12, 21 and 6 patients displayed higher HHLA2, B7H3, IDO-1, PD-L1 and galectin-9 expression in the tumor subregion, respectively." (PMID 35145510, 2021). "Besides, the cDC3_LAMP3 cells that highly expressed LAMP3, IDO1, and CCL21 associated with high maturation and migration ability were also considered as tumor-promoting immune cells." (PMID 35087839, 2021). "And the anti-tumor effect of dexamethasone could be rescued by overexpression of PD-L1 or IDO1 in cancer cells." (PMID 34175886, 2021). "IDO1 might restrict the inflow of tryptophan from blood to tumor and produce tumor-toxic metabolites in endothelial cells, thus decreasing tumor growth." (PMID 34322485, 2021). "Although these studies revealed that up-regulation of IDO1 was beneficial to the suppression of cancer to some degree, more studies indicated that overexpressed IDO1 was related to immunosuppression and played an adverse role in the process of tumor development." (PMID 34717710, 2021). "Counteracting IDO1 activities has resulted in the reactivation of anticancer immune responses in animal studies with tumour models, suggesting that blockage of IDO1 may also represent a promising therapeutic candidate for HRPC." (PMID 33921181, 2021). "Therefore, immune surveillance will be strongly suppressed in a TRP-deprived tumour microenvironment driven by an overactive IDO1/TDO2 tumour." (PMID 34680327, 2021). "In conclusion, aberrant activation of KP as well as a solid correlation between high expression of IDO1 or IDO1/TDO and tumor progression or poor patients’ outcome should be kept in mind when selecting the candidate tumor type for clinical trials of IDO1 inhibitors." (PMID 33557876, 2021). "Indoleamine 2,3-dioxygenase 1 (IDO1) is a normal endogenous mechanism of acquired peripheral immune tolerance and may therefore be tumor-promoting." (PMID 34557196, 2021). "However, Vγ9Vδ2 T cells combined with IDO1 inhibitor 1-Methyl-L-tryptophan (1-MT) or Lindrostat showed substantial inhibitory effects on MDA-MB-231 tumor cells." (PMID 34381711, 2021). "IDO1 is a cytosolic monomeric, heme-containing enzyme, which is now considered an authentic immune regulator and represents one of the promising drug targets for tumor immunotherapy." (PMID 35003126, 2021). "While the literature suggests that this could be accounted for by cell-intrinsic and -extrinsic factors, a more thorough exploration of what dictates tumor IDO1 expression would be valuable—for example, in helping to stratify treatment with IDO1 inhibitors." (PMID 33831358, 2021). "However, B7H3, IDO-1 and Galectin-9 positivity on tumor cells were only seen in 21.0% of cases, despite all showing predominantly stromal expression." (PMID 35145510, 2021). "In addition, IDO1 expression is induced, as is that of PD-L1, when some degree of inflammation occurs in the tumor, e.g., the presence of proinflammatory mediators, such as IFN-γ, as a mechanism of adaptive resistance against infiltrating T cells." (PMID 33467713, 2021).
tumor (continued). "As a part of a tumor immune escape mechanism, IDO1 overexpression has been described in numerous human cancer types not only in tumor lesions by tumor cells and other components of the TME like endothelial cells, myeloid derived suppressor cells (MDSCs), DCs, but also in tumor draining lymph nodes." (PMID 33557876, 2021). "There are two main Trp decomposition pathways concerned with IDO1-mediated tumor immune escape." (PMID 33883013, 2021). "However, the IDO1 inhibitor, epacadostat, has failed in phase III clinical trials; its limited capacity to inhibit IDO1 expression at tumor sites was regarded as a key reason for clinical failure." (PMID 33828565, 2021). "Future studies should explore the relations among SOX2, the IFN/IDO1 cascade, and tumour dormancy." (PMID 34539663, 2021). "Interestingly, due to the activation of AHR, tumor cells express high levels of IDO1 and TDO2 to promote plasticity." (PMID 33692337, 2021). "IDO1 catalyzes the initial oxidation of L-tryptophan (L-Trp) and induces the accumulation of kynurenine metabolites, which lead to the suppression of T-cell and are responsible for tumor cells to escape the monitoring and clearance of the immune system." (PMID 33883013, 2021). "An increasing amount of evidence reported that CD8+ T cells in the tumor microenvironment could produce IFNγ, leading to the upregulation of the PD-1/PD-L1 axis and IDO1." (PMID 32346613, 2020). "This is in line with IDO1 expression in B16-F10 tumors being of stromal origin, but it does not preclude that specific hematopoietic cell types that are less abundant within the tumor microenvironment may express IDO1." (PMID 32231867, 2020). "The ratio of IDO1 positive vessels inversely correlated with the proliferating tumour cells." (PMID 32227579, 2020). "Although there is a difference between these tumours regarding their correlation with IDO1 expression level and clinical outcome, both investigations appear to have a positive correlation between the presence of tumour‐infiltrating T cells and increased IDO1 expression." (PMID 32227579, 2020). "Additionally, IDO-1 expressing tumor cells respond to tryptophan shortage by expressing amino acid transporter genes (i.e., SLC7A11, SLC1A4, and SLC1A5)." (PMID 33330446, 2020). "Indoleamine 2,3-dioxygenase (IDO1) plays an important role in tumor immune evasion." (PMID 32733806, 2020). "Our results showed that Stat1 ablation and corresponding loss of IDO1+ tumor cells did not affect nuclear β-catenin levels in sporadic ApcMin tumors." (PMID 32444775, 2020). "However, a strong correlation was observed between protein expression of STAT1 and IDO1 in tumor cells and stroma cells." (PMID 32444775, 2020). "As a negative feedback response to the interferon γ (IFNγ) released by T lymphocytes at the tumor site, IDO-1 is activated and degrades tryptophan, further inducing T lymphocytes’ proliferation arrest and ­apoptosis by triggering an adaptive evasion from the immune control." (PMID 32296574, 2020). "The simultaneous presence of IDO1 and IL-10 can also influence non-infective inflammation such as that associated with tumor development." (PMID 32194572, 2020). "Thus, IDO1-Kyn-AhR-p27 pathway was proposed as a mechanism which explains how high concentration of IFN-γ induces tumor dormancy." (PMID 33005420, 2020). "Besides, the indoleamine 2,3-dioxygenase (IDO1), a rate-limiting enzyme, is also discussed as a potential key target on tumor immune evasion and generates immunosuppressive metabolites through oxidizing tryptophan into kynurenine." (PMID 32733806, 2020). "Moreover, the potential predictive value of the changes of tumor IDO1 expression and CD8+TILs status on pathologic response and clinical outcome was further evaluated." (PMID 32733806, 2020).